GATA6 (GATA binding protein 6)
Diseases named in the same sentence as GATA6 in open-access papers (continued):
Sharing a sentence is not in itself a finding about the gene and the disease.
oral cancer (2 papers, 2021). "In studying the expression of GATA6 in oral cancer cell lines and understanding its role in the development of oral cancer, research on GATA6 will provide innovative ideas for tumor prevention measures, targeted therapy, and other treatment methods." (PMID 34006300, 2021). "Among the four oral cancer cell lines selected in the experiment, GATA6 was expressed in both mRNA and protein levels in two cell lines, only in mRNA level in one cell line and no expression in one cell line." (PMID 34006300, 2021). "This study aimed to investigate the expression level of the GATA6 gene in different oral cancer cells." (PMID 34006300, 2021). "Further research is still needed to investigate the role of GATA6 in the incidence and progression of oral cancer." (PMID 34006300, 2021). "The overall aim of this study was to examine the role of GATA6 in the development of oral cancer." (PMID 34006300, 2021). "This experiment preliminarily confirmed the expression of GATA6 in some oral cancer cell lines." (PMID 34006300, 2021). "Consequently, we conducted this study to examine the expression level of the GATA6 gene in oral cancer cells." (PMID 34006300, 2021). "In addition, GATA6 increased in oral carcinoma tissues compared with the adjacent normal tissues." (PMID 34006300, 2021). "The GATA6 gene may be related to the occurrence and progression of certain oral cancers." (PMID 34006300, 2021). "This study preliminarily established the expression of the GATA6 gene in oral cancer cells, but there were differences in the protein-level and gene-level expression in the different cell lines, revealing that GATA6 may be involved in the incidence of oral cancer." (PMID 34006300, 2021). "Additionally, ICAM-1 has been reported to interact with many signaling pathways in human diseases, such as ICAM-1-PI3K/Akt/GSK-3β/GATA-6 pathway in atheroscherosis, ICAM-1-IL-6/AKT/STAT3/NF-κB pathway in chronic obstructive pulmonary disease, and ICAM-1-PGE2/EP1 pathway in oral cancer." (PMID 33506255, 2021).
pancreatitis (2 papers, 2008 to 2023). Inflammation of the pancreas. "A failure to achieve complete acinar maturation is associated with more severe damage and delayed recovery during caerulein-mediated pancreatitis in several genetic mouse models including those where Gata6, Mist1, and Ptf1a are inactivated in the pancreas." (PMID 37353485, 2023).
Patent ductus arteriosus (2 papers, 2019 to 2022). In utero, the ductus arteriosus (DA) serves to divert ventricular output away from the lungs and toward the placenta by connecting the main pulmonary artery to the descending aorta. "Accordingly, human mutations in GATA6 have been identified in cases of patent ductus arteriosus (PDA) and atrial fibrillation." (PMID 35835508, 2022).
persistent truncus arteriosus (2 papers, 2025). A rare congenital cardiovascular disorder characterized by the failure of the embryologic structure truncus arteriosus to divide into the aorta and pulmonary trunk. "Human variants of GATA6 were first reported in individuals with persistent truncus arteriosus (PTA)." (PMID 40076735, 2025).
Protein-losing enteropathy (2 papers, 2016 to 2024). Abnormal loss of protein from the digestive tract related to excessive leakage of plasma proteins into the lumen of the gastrointestinal tract. "Other malformations of the digestive system have been described in patients with GATA6: biliary atresia, intestinal malrotation, and protein-losing enteropathy." (PMID 39596087, 2024).
pulmonary hypertension (2 papers, 2009 to 2023). Increased pressure within the pulmonary circulation due to lung or heart disorder. "To test the therapeutic effects of DMF on pulmonary hypertension in Gata6 CKO mice, we first assessed the effect of DMF on oxidative stress." (PMID 37087509, 2023). "We showed that the expression of GATA-6 mRNA and protein was down-regulated in this pulmonary hypertension model, which was reversed by simvastatin administration." (PMID 19842842, 2009). "The aim of present study was to investigate the expression of GATA-6 gene in experimental pulmonary hypertensive rats and explore the effect of regulation of GATA-6 expression by simvastatin on pulmonary vascular remodeling." (PMID 19842842, 2009). "In the present study, we also found that down-regulation of GATA-6 expression was reversed in pulmonary hypertensive rats treated with simvastatin." (PMID 19842842, 2009). "To test the therapeutic effects of DMF on pulmonary hypertension in Gata6 CKO mice, we measured right ventricle systolic pressure, as well as pulmonary acceleration time as a fraction of ejection time (PAT/ET) and the weight ratios of the right ventricle to the left ventricle plus septum." (PMID 37087509, 2023). "Based on these studies, we speculate that activity of transcription factor GATA-6 may be regulated by disturbed laminar shear stresses occurring in pulmonary hypertension." (PMID 19842842, 2009). "In this study, we found that down-regulation of GATA-6 expression was concurrent with development and progression of pulmonary hypertension, right ventricular hypertrophy, arterial medial hypertrophy, and neointimal formation in the neointimal pulmonary hypertensive model." (PMID 19842842, 2009). "Further studies will be performed to investigate the mechanism of GATA-6 expression by regulated by simastatin and examine GATA-6 expression in the lung tissue of human patients with pulmonary hypertension." (PMID 19842842, 2009).
sebaceous tumors (2 papers, 2019 to 2020). "We previously identified GATA6 as a marker of sebaceous differentiation in benign and malignant mouse and human sebaceous tumours." (PMID 33082341, 2020). "Our data indicate a role of Gata6 in the physiopathology of sebaceous tumors, particularly in relation to DNA mismatch repair." (PMID 30886049, 2019). "Thus, Gata6 could be a useful biomarker for diagnostic pathology of sebaceous tumors." (PMID 30886049, 2019). "In humans, sebaceous tumors harbor a high level of expression of Gata6." (PMID 30886049, 2019). "Therefore, in the present work, we sought to explore the role of Gata6 in establishing the sebaceous lineage and to understand the link between Gata6 and Lef1 in the context of sebaceous gland tumors." (PMID 30886049, 2019). "Eighteen out of 19 human sebaceous tumors were Gata6‐positive, regardless of their malignancy grade." (PMID 30886049, 2019).
skin tumors (2 papers, 2019 to 2020). "In mice overexpressing mutant Lef1, Gata6 ablation increases the total number of skin tumors yet decreases the proportion of SG tumors." (PMID 30886049, 2019). "To examine whether the observations in mice were relevant to human skin tumors, we first confirmed that Gata6 was expressed in the same locations in human as in mouse adult skin." (PMID 30886049, 2019). "Furthermore, human skin tumors with sebaceous differentiation expressed Gata6." (PMID 30886049, 2019).
triple-negative breast carcinoma (2 papers, 2019 to 2026). An invasive breast carcinoma which is negative for expression of estrogen receptor (ER), progesterone receptor (PR), and human epidermal growth factor receptor 2 (HER2). "Moreover, comparison of the expression of UTX, Vimentin, and GATA transcription factor family in normal and triple-negative breast cancer samples using the TCGA database also show marked downregulation of GATA3 and UTX, whereas GATA6 was significantly upregulated." (PMID 31685800, 2019).
abdominal aortic aneurysm (1 paper, 2023). Enlargement and ballooning of the vessel that supplies arterial blood to the abdomen, pelvis and legs. "Epigenetic modifications of GATA6 are found in endothelial cells of patients with abdominal aortic aneurysms." (PMID 37662558, 2023).
adrenal cortical carcinoma (1 paper, 2022). "Expression of master-regulator SF1 and the key adrenal transcription factors GATA4 and GATA6 in the HAA1 line was present, but lower than that in the control NCI-H295R human adrenal cortical carcinoma cell line." (PMID 36614027, 2022).
adrenocortical adenomas (1 paper, 2008). "It is noteworthy that GATA-6 is present in adrenocortical adenomas, but diminishes in carcinomas, suggesting that also Gata6 may become methylated during tumorigenesis." (PMID 18405344, 2008).
adrenocortical tumors (1 paper, 2010). "Expression of Gata6 is significantly depressed in most human adrenocortical tumors and it has been hypothesized that decreased expression of Gata6 may be an important event for the escape of tumor cells from normal control mechanisms." (PMID 20959002, 2010).
Alagille syndrome (1 paper, 2017). "Mutations in GATA6 cause PTA and haploinsufficiency of JAG1 (a Gata6 target detected in this study) causes Alagille syndrome, a congenital disorder associated with OFT and great vessels defects." (PMID 28952437, 2017).
atrial fibrillation (1 paper, 2019). A disorder characterized by an electrocardiographic finding of a supraventricular arrhythmia characterized by the replacement of consistent P waves by rapid oscillations or fibrillatory waves that vary in size, shape and timing and are accompanied by an irregular ventricular response. "In addition, sequence variations in the splicing sites and coding regions of GATA6 have also been reported in other cardiovascular diseases such as dilated cardiomyopathy (DCM) and cardiac conduction system (CCS) including atrial fibrillation (AF)." (PMID 31781165, 2019).
atrophic gastritis (1 paper, 2008). "GATA-4 and GATA-6 are also expressed in hyperplastic neuroendocrine cells associated with atrophic gastritis." (PMID 18405344, 2008).
Cerebellar hypoplasia (1 paper, 2025). Cerebellar hypoplasia is a descriptive term implying a cerebellum with a reduced volume, but a normal shape and is stable over time. "Subsequent research revealed that PTF1A and GATA6 mutations could also cause pancreatic agenesis, often in association with additional congenital anomalies such as cardiac defects, biliary atresia, or cerebellar hypoplasia." (PMID 41393705, 2025).
clear cell carcinoma (1 paper, 2009). "Loss of GATA6 was found in 55/82 (67%) of serous carcinomas, 1/12 (8.3%) of mucinous carcinomas, 10/12 (83%) of clear cell carcinoma, and 5/5 (100%) of endometroid carcinomas." (PMID 19649254, 2009).
dysgerminoma (1 paper, 2023). A malignant germ cell tumor characterized by the presence of a monotonous primitive germ cell population. "For example, all of the YST strongly expressed GATA-4, GATA-6, and HNF-4, while dysgerminomas partly expressed GATA-4 (five out of eight), though they did not express GATA-6 or HNF-4." (PMID 37372675, 2023).
endometrial cancer (1 paper, 2021). Primary or metastatic malignant neoplasm involving the endometrium (mucous membrane that lines the endometrial cavity). "Another researcher used immunohistochemistry to detect the expression of GATA6 in endometrial cancer tissues and the expression difference of GATA6 with atypical endometrial hyperplasia and normal endometrial tissue was compared." (PMID 34006300, 2021). "It was also suggested that the distinctive degree of endometrial cancer, TNM stage, distant metastasis, and the infiltration depth of the muscular layer was closely related to the expression of GATA6." (PMID 34006300, 2021).
endometrioid ovarian cancer (1 paper, 2009). "GATA4 and GATA6 were found to be absent in high percentages (80 to 90%) of serous, clear cell, and endometrioid ovarian cancer examined." (PMID 19649254, 2009).
endothelial dysfunction (1 paper, 2023). In vascular diseases, endothelial dysfunction is a systemic pathological state of the endothelium (the inner lining of blood vessels) and can be broadly defined as an imbalance between vasodilating and vasoconstricting substances produced by (or acting on) the endothelium. "Notably, mice with conditional deletion of Gata6 in endothelial cells (Gata6-CKO) develop PH spontaneously, suggesting that GATA6 downregulation is an early and key event that leads to endothelial dysfunction and the development of PH15." (PMID 37087509, 2023).
fetal growth restriction (1 paper, 2024). A fetus that does not grow beyond the 10th percentile of conventionally accepted weight for gestational age. "Placental mRNA expression was examined for the 8 genes enriched in isolated trophoblast side-population cells (CXLC8/IL8, ELL2, GATA6, HK2, HLA-DPB1, INTS6, SERPINE3, UPP1) in placentas obtained from participants with early onset preeclampsia (n = 78) or fetal growth restriction (n = 30)." (PMID 39028417, 2024).
Gastric Metaplasia (1 paper, 2008). Intestinal metaplasia of the gastric mucosa is an intermediate precancerous gastric lesion in the gastric cancer cascade from chronic gastritis and atrophy to dysplasia and adenocarcinoma. "Furthermore, TFF and mucin proteins have been shown to be present in esophageal and gastric metaplasias, similarly to GATA-4 and GATA-6 (this study)." (PMID 18405344, 2008).
germinoma (1 paper, 2020). A malignant germ cell tumor arising in the central nervous system. "While this particular sample showed higher expression of GATA6, FOXA2, or HNF4A and hypermethylation of RASSF1, RUNX3, HIC1, or APC, its methylation pattern was partially common to that of germinomas or ECs." (PMID 32999426, 2020).
glaucoma (1 paper, 2026). Increased pressure in the eyeball due to obstruction of the outflow of aqueous humor. "However, recognizing the specific genetic etiology is critical for predicting and managing the associated multi-system comorbidities, such as monitoring for glaucoma in GLIS3 patients or cardiac defects in GATA6 carriers." (PMID 41614934, 2026). "Similarly, patients with GATA6 mutations require regular cardiac evaluations, while those with GLIS3 defects must be monitored for glaucoma and thyroid dysfunction." (PMID 41614934, 2026).
Granuloma (1 paper, 2025). A compact, organized collection of mature mononuclear phagocytes, which may be but is not necessarily accompanied by accessory features such as necrosis. "Among structural cells, the expression of key tissue development genes (MAPK14, GATA6, FOXF1, VEGFA) were markedly elevated in both endothelial and epithelial cell populations derived from MAH granulomas." (PMID 41586350, 2025).
head and neck squamous cell carcinoma (1 paper, 2022). A squamous cell carcinoma that arises from any of the following anatomic sites: lip and oral cavity, nasal cavity, paranasal sinuses, pharynx, larynx, and salivary glands. "In patients with head and neck squamous cell carcinoma (HNSCC), upregulation of CALM1, CYCS, THBS1, MYC, GATA6, and SPRED3 was strongly associated with a poor prognosis." (PMID 36239104, 2022).
Hernia (1 paper, 2025). "In this context, we aimed to investigate the expression levels of GATA6 and TBX3 in hernia sacs obtained from patients with IIH and in prepuce tissues from circumcised healthy boys in our study population." (PMID 40622564, 2025). "The aim of the study is to examine the expression levels of the GATA6 and TBX3 genes in hernia sacs from patients with indirect inguinal hernia (IIH) in the Trakya region, Türkiye and shed light on the etiology of this common surgical disease in childhood." (PMID 40622564, 2025).
Insulin resistance (1 paper, 2019). Increased resistance towards insulin, that is, diminished effectiveness of insulin in reducing blood glucose levels. "Alteration in GATA6 is responsible for the development of NIDDM, but this gene may be identified with insulin resistance." (PMID 30678306, 2019).
intervertebral disc degeneration (1 paper, 2025). "This study explored the role of ferroptosis in intervertebral disc degeneration (IVDD), and identified GATA6 as a key regulator of this process." (PMID 39897029, 2025).
kidney cancer (1 paper, 2019). Primary or metastatic malignant neoplasm involving the kidney. "In kidney cancer, GATA2, GATA3, GATA5 and GATA6 were mostly downregulated." (PMID 30872657, 2019).
laryngeal carcinoma (1 paper, 2021). Carcinoma that arises from the laryngeal epithelium. "Some studies have also found the expression of GATA6 in laryngeal cancer and the corresponding para cancer tissues and normal laryngeal mucosal tissues of healthy people." (PMID 34006300, 2021).
Lynch syndrome (1 paper, 2019). An autosomal dominant hereditary neoplastic syndrome characterized by the development of colorectal carcinoma and a high risk of developing endometrial carcinoma, gastric carcinoma, ovarian carcinoma, renal pelvis carcinoma, and small intestinal carcinoma. "To further study the functional impact of Gata6 on the MMR pathway, we used two methods that are key to diagnosing Muir–Torre syndrome and Lynch syndrome: microsatellite instability (MSI) testing and immunohistochemistry for MMR proteins." (PMID 30886049, 2019).
meningioma (1 paper, 2015). A generally slow growing tumor attached to the dura mater. "In summary, this study provided evidence that p14ARF, RASSF1A, p15INK4B (CDKN2B), RUNX3, GATA6, p16INK4A (CDKN2A), NDRG2 and to lesser extent ATM and RARβ promoter methylation are associated with the development of meningiomas." (PMID 25648363, 2015). "Thus, GATA6 promoter methylation in meningioma may play certain role in menigioma development, although cannot be considered as a biomarker candidate." (PMID 25648363, 2015). "The aim of this study was to evaluate the methylation status of 12 cancer-related genes, namely ERCC1, hMLH1, ATM, CDKN2B (p15INK4B), p14ARF, CDKN2A (p16INK4A), RASSF1A, RUNX3, GATA6, NDRG2, PTEN, and RARβ, in 44 meningioma samples of WHO grade I and II." (PMID 25648363, 2015).
mucinous carcinomas (1 paper, 2009). "Thus, the expression of GATA4 and GATA6 distinguishes mucinous carcinomas from other histological subtypes." (PMID 19649254, 2009).
mucinous ovarian carcinomas (1 paper, 2009). An invasive malignant neoplasm that arises from the ovary and is characterized by the presence of malignant epithelial cells that contain intracytoplasmic mucin and may resemble the epithelial cells of the endocervix or gastrointestinal tract. "This study suggests that the expression status of GATA4 and GATA6 may dictate distinct pathologic pathways leading to serous or mucinous ovarian carcinomas." (PMID 19649254, 2009). "In contrast to other histological subtypes, mucinous ovarian carcinomas generally are positive for GATA4 and GATA6 expression." (PMID 19649254, 2009).
myeloma (1 paper, 2020). "Moreover, GATA6 may regulate the WNT signaling pathway, which is dysregulated in myeloma, thereby methylation of BM742401 may link to the regulation of the Wnt signaling pathway, playing a role in the pathogenesis of myeloma." (PMID 32855620, 2020).
nematode infection (1 paper, 2023). "The transition to tissue residency altered macrophage function, and GATA6+ tissue-resident macrophages were required for host resistance to nematode infection." (PMID 36948193, 2023). "This study reveals an unappreciated role for adaptive immunity in controlling macrophage tissue residency and for GATA6+ macrophages in controlling nematode infection." (PMID 36948193, 2023).
oral squamous cell carcinoma (1 paper, 2021). "Previous research has confirmed that GATA6 is expressed in oral squamous cell carcinoma tissues of 21 groups, and the expressions of GATA6 were different due to the different clinical stages, pathological grades, and potential metastatic ability of the selected cancer tissues." (PMID 34006300, 2021).
Ovarian cyst (1 paper, 2009). The presence of one or more cysts of the ovary. "Strikingly, all ovaries of GATA6 (+/−) genotype exhibited some abnormalities: Some ovaries have extensive proliferative lesions of the surface epithelia, and the others have large ovarian cysts that are positive for cytokeratin." (PMID 19649254, 2009).